MIR3666 (microRNA 3666)
Synonyms: hsa-mir-3666
Gene: MicroRNA gene on chromosome 7 (114,653,345 to 114,653,455, forward strand). Ensembl gene ENSG00000272230.
Homologues: Orthologues: chimpanzee MIR3666 (100% identical), macaque MIR3666 (100% identical).